CD8A (CD8 subunit alpha)
Diseases named in the same sentence as CD8A in open-access papers (continued):
Sharing a sentence is not in itself a finding about the gene and the disease.
cancer (continued). "We validated that high CD8A and CXCR3 levels were associated with a better survival rate in all cancer patients treated with immunotherapies." (PMID 38953994, 2024). "It turned out that the protein level of CD8α determined by IHC staining was lower in cancer tissues that were characterized with higher expression of PDL1 protein, and vice versa." (PMID 39421264, 2024). "Herein we show that at the RNA level, TIMP1 expression does correlate with CD8A expression in the TME of several cancer types of the PANCAN study, extending its pro-inflammatory roles in cancer." (PMID 38777826, 2024). "The expression levels of PD-L1 and CD8A were positively correlated overall and in most cancer types." (PMID 37064155, 2023). "At the gene-level, the cytolytic granzyme A (GZMA) and K (GZMK) enzyme, CD8A and the chemokine CXCL10 illustrious of T and NK-cells and the testis antigen SPAG5 were associated with infiltration to cancer tissue." (PMID 37391505, 2023). "Then, we aimed to interrogate the role of CD8A in TME of diverse cancer types at single-cell resolution and its correlation with malignant phenotype and functional states." (PMID 36035168, 2022). "In this work, we investigated functional identity information of CD8A at single-cell resolution, with tSNE plots originating from multiple cancer datasets manifesting that CD8A consistently exhibited low expression levels in TME." (PMID 36035168, 2022). "The results revealed that CD8A was a useful prognostic factor among several types of cancers including BCa, and patients with low CD8A expression were prone to having poor survival outcomes." (PMID 36230788, 2022). "We further investigated the association between CD8A expression and IC50 values of seven drugs for anti-cancer treatment." (PMID 36230788, 2022). "We then investigated the correlation between CD8A expression and 20 TIICs in a cohort of 30 cancer types." (PMID 36230788, 2022). "Following that, we investigated the utility of CD8A in evaluating therapeutic responses to various antitumor drugs in clinical cancer cohorts." (PMID 36035168, 2022). "Representing < 0.2% of infiltrating human CD45+ leukocytes, CD141+ CD8a+ XCR1+ CLEC9A+ BATF3+ cDC1 is a rare population in human cancers." (PMID 36230990, 2022). "Specifically, we found a convergently positive correlation between CD8A and all six major types of immune cells of the pan-cancer TME." (PMID 36035168, 2022). "We used TCGA database to perform a differential analysis of CD8A expression between cancer and normal tissues to score the transcriptomic patterns of CD8A." (PMID 36035168, 2022). "Pan-cancer analysis, meta-analysis and multivariate Cox regression analysis were performed to further comprehensively explore the prognostic value of CD8A in cancer patients, especially BCa patients." (PMID 36230788, 2022). "We then found that CD8A was correlated with six major immune cell types, and immunosuppressive cells in multiple cancer types." (PMID 36035168, 2022). "We also aimed to explore the relationship between the epigenetic modification status of CD8A and cancer patient prognosis, attempting to uncover deeper mechanisms of CD8A influencing tumorigenesis and treatment responses." (PMID 36035168, 2022). "In two immunotherapy datasets including IMvigor210C and GSE93157, CD8A acted as a protective gene for cancer patients treated with immunotherapy." (PMID 36230788, 2022). "The findings above shed light on the distinct CD8A expression patterns and their enormous potential as a robust biomarker for predicting prognosis and cancer stage." (PMID 36035168, 2022). "In the field of cancer studies, it was revealed that CD8α+ DCs can release type I IFN via the STING pathway, resulting in antigen cross-presentation and the priming of CD8+ T cells." (PMID 36010836, 2022). "Obviously, CD8A expression was positively correlated to the proportions of CD8+ T cells and Macrophages M1 in pan-cancer." (PMID 36230788, 2022).
cancer (continued). "These authors showed that the oral application of antibiotic contributed to the decrease in cancer growth which correlated with an increased number of IL-12 producing CD8α DCs." (PMID 33970783, 2021). "A large number of studies have shown that CD8a+ DCs play a vital role in inducing protective CD8+ cytotoxic T cell response, which are essential for radical curing of malignant tumors, viruses, and other pathogen infections." (PMID 32655564, 2020). "Overall, the observations suggest a conundrum regarding the functional failure of cytotoxic CD8α+ T in killing cancer cells during chemotherapy." (PMID 31752354, 2019). "pS14-WWOX7-21 peptide strongly induces the expression of cytotoxic CD8α+ T cells, but these cells fail to suppress cancer growth." (PMID 31752354, 2019). "On the contrary, there is a strong correlation between the expression level of PD-L1 and CD8A in those cancer tissues (Pearson's r = 0.64, p < 10-7)." (PMID 31523194, 2019). "We found that most cancers show a higher HR of PD-L1 expression adjusted for CD8A by multivariate Cox-Ph model, with above half of them larger than 1, indicating that PD-L1 are more likely to be associated with poor outcome after adjusting for CD8A expression." (PMID 31523194, 2019). "Several were surface proteins expressed on immune cells, e.g., CD8A, and PD-1, or on cancer cells and affecting immune activity, e.g., PD-L1, FASL, and notably PD-1 and its ligand PD-L1 were similarly upregulated." (PMID 29587383, 2018). "Similar to the whole population with all stages of cancer, patients with low-CD8A expression and high-CD274 expression had a poorer prognosis." (PMID 30318514, 2018). "Because the CTL immune response has been sought to effectively kill cancer cells, CD8α+ cDC activation and maturation has been demonstrated as a promising strategy for cancer immunotherapy." (PMID 28423736, 2017). "Certain types of cancer cells express molecular structures specifically recognised by CD8α + dendritic cells (DCs), which subsequently interact with cytotoxic T cells to induce cancer cell death." (PMID 28596706, 2017). "Comparable characteristics of CD141+ mDCs with mouse CD8α+ DCs suggest them to be excellent targets for DC-based cancer immunotherapy." (PMID 28536413, 2015). "From these clusters, five major cell types were identified via classical cell markers, including T cells (CD3E, CD8A, CD3D), B cells (CD19, MS4A1, CD79A), myeloid cells (CD14, CD68, LYZ), endothelial cells (PECAM1, VWF, CDH5) and cancer-associated fibroblasts (CAFs) (ACTA2, FAP, PDGFRB)." (PMID 39941131, 2025). "To confirm this hypothesis, we herein depleted CD8+ T cells using an anti-CD8α antibody, and examined the anti-cancer effect of IPG0521m." (PMID 40186298, 2025). "Notably, TIMP1 displayed a significant positive correlation with CD8A infiltration across most cancer types." (PMID 38777826, 2024). "Moreover, preclinical studies have explored the use of cDC1s in some types of cancers using syngeneic mouse models and mouse CD8α+ DCs that are putative equivalents to human CD141+ DCs30." (PMID 36596856, 2023). "Consequently, the RNA-based version of SIA (ratio of CD8A to C1QA) was predictive for survival in independent RNAseq data sets from these six cancer types." (PMID 36724681, 2023). "For example, the sensitivity hierarchy that we observe [STARS > TruCs > CAR (CD28 hinge) > CAR (CD8a hinge) > CAR (IgG1 hinge)] suggests that standard CARs may be preferred for targeting cancers that overexpress antigens also expressed on normal cells." (PMID 36598945, 2023). "Besides, high intratumoral expression of CCL5 is correlated with better prognosis and strongly correlated with intratumoral CD8A expression across multiple cancer types according to our analysis of TCGA datasets." (PMID 36352411, 2022). "Interestingly, we found that CD8A presented consistently low expression levels in TME of the other four cancer types and was only expressed in a small portion of cells." (PMID 36035168, 2022).
cancer (continued). "Surprisingly, correlations between CD8A and Treg and CAFs varied by cancer type, and the underlying mechanism for this ambiguous phenomenon may be due to the heterogeneity of TME of pan-cancers." (PMID 36035168, 2022). "CD8A encodes CD8 antigen, so CD8A expression may be associated with survival outcomes, immune cell infiltration and immunotherapeutic response in cancer patients." (PMID 36230788, 2022). "Previous studies have reported some biomarkers related to cancer immunotherapeutic response such as TMB and the expression of some critical immune checkpoint genes, so we further explored the association of CD8A with TMB and critical immune checkpoint genes." (PMID 36230788, 2022). "The results revealed that CD8A expression was highly correlated to most of TIICs in pan-cancer." (PMID 36230788, 2022). "We also analyzed the correlation between PD-L1 and PD-1 expression values and m6AScore, and the results showed that 23 out of 33 cancers had a significant correlation between m6AScore and CD274; 20 out of 33 cancers had a significant correlation between m6AScore and CD8A." (PMID 35265626, 2022). "Thus, CD8A can not only be a useful prognostic factor in BCa patients but also a predictive marker of immunotherapeutic response in cancer patients treated with immunotherapy." (PMID 36230788, 2022). "A previous study for pan-cancer has reported that high status of CD8A with high expression of PD-L1 might be a predictive marker of immunotherapeutic response." (PMID 36230788, 2022). "Finally, we tested CD8A as a therapeutic biomarker for multiple antitumor agents’ or compounds’ responsiveness on various cancer cell lines and cancer cohorts." (PMID 36035168, 2022). "However, few studies clarified the association between CD8A and immunotherapeutic response, so we further investigated the prognostic value of CD8A in cancer patients treated with immunotherapy in two datasets (IMvigor210 and GSE93157)." (PMID 36230788, 2022). "Taken together, above results elucidated that CD8A could efficaciously function as a therapeutic response biomarker in various cancer cell lines and cohorts treated with multiple anticancer agents." (PMID 36035168, 2022). "Pan-cancer analysis revealed that CD8A was related to TMB in several types of tumors." (PMID 36230788, 2022). "In terms of immunity, invasiveness was positively correlated with the immune score and diverse immune signatures across several cancer types, including the expression of CD8A, TIL infiltration, CYT, the IFN response, and an expression signature of antigen processing and presenting machinery." (PMID 33766047, 2021). "In the iC3 subtype, which was associated with the most aggressive SKCM cases, FAM135B gene mutation frequencies were increased, while CD8A, GBP5, KIAA0040, and SAMHD1 expression were downregulated, suggesting that these genes play important roles in cancer development and immune responses." (PMID 32639949, 2020). "The prognostic values of PD-L1 and CD8A are highly correlated and interactive across cancer types." (PMID 31523194, 2019). "Interestingly, we observed a favorable prognostic value (hazard ratio (HR) < 1) in the majority of cancer types for both PD-L1 and CD8A." (PMID 31523194, 2019). "In addition, the authors suggest that both cytosolic DNA sensing and Batf3-dependent CD103+/CD8α+ DCs are essential to the antitumor efficacy of this mode of cancer immunotherapy." (PMID 30626434, 2019). "Therefore, we used naturally occurring mouse spleen CD8α+ cDC1 in order to test the suitability of cDC1s as basis for effective cancer therapy." (PMID 30961656, 2019). "In fact, small size platforms (<200 nm) may drain freely to LNs, being thus taken up by LN-resident DC subsets such as CD8α+, which seems an advantage for cancer immunotherapeutic approaches." (PMID 25505783, 2014).
cancer (continued). "In accordance with the generally accepted cancer-immunity cycle concept, these APCs subsequently drive the anti-tumorigenic responses by travelling towards the lymph nodes where they present the xeno-antigens to residing CD8α+ T-cells, priming and activating effector T-cell responses." (PMID 37928528, 2023). "In addition, we also found that patients with high CD8A expression were more sensitive to several drugs for anti-cancer treatment, which may broaden the application of CD8A in clinical practice." (PMID 36230788, 2022). "In addition, whether the findings about TFs instructing the development of CD4+ CD8α+ IELs are generalizable to other tissue compartments or to cancer requires confirmation." (PMID 34910940, 2021). "The IDO1/CD8A classifier may be suitable for use in the prediction of cancer development." (PMID 33425745, 2020). "First, to investigate whether CTL and PD-L1 show different associations with clinical outcome, we estimated the CTL level using the expression level of CD8A, and evaluated the prognostic value of CD8A and PD-L1 expression in 15 solid TCGA cancer types using Cox proportional hazard analysis (Cox-PH)." (PMID 31523194, 2019). "Thus, therapeutically inducing CD8A could enhance the function of cytotoxic T lymphocytes, enabling them to kill more cancer cells." (PMID 31715586, 2019). "Extending our analysis to human cancers, we found that MBNL1 expression positively correlates with CD8A expression and cytolytic T cell activity, suggesting a conserved role for MBNL proteins in regulating T cell infiltration and function." (PMID 40305509, 2025). "CD8a, part of the CD8 glycoprotein complex, is predominantly found on cytotoxic T cells, crucial for identifying and destroying cancer cells." (PMID 41583493, 2025). "We explore further the gene regulatory network of PID CD8 TCR Downstream Pathway, we discovered that TNFRSF9 and CD8A were expressed at a high level in above all cancers." (PMID 38720108, 2024). "We found that single-cell RNA sequence data derived from patients with PDAC showed the expression level of HRH1 in cancer cells is negatively correlated with the expression level of CD3D+, CD8A+ T cells." (PMID 38715057, 2024). "Further insights into the distinct populations and functional specializations of NKT cells, including CD8A+ NKT-like cells, highlight the complexity of the immune system’s interaction with cancer." (PMID 38975339, 2024). "CD8A, FCGR3A, and PTPRC are identified as candidate biomarkers in various cancers or important molecules in PCa patients with bone metastases." (PMID 37494663, 2023). "In the TIMER2.0 database, we further confirmed that in pan-cancer, IFNG had a general correlation with PD-L1 and CD8A." (PMID 36756126, 2023). "Most cancer entities exhibited significantly positive Pearson correlations coefficients, with the highest coefficients for CD4, CD8A, and CTLA4." (PMID 36672341, 2023). "Further analyzing transcriptomic data exhibited significantly positive Pearson correlation coefficients for most cancer entities between CXCR4 and the T cell co-receptors CD4 and CD8A, as well as IRF1 and CTLA4." (PMID 36672341, 2023). "Of those, only T-cell-inflamed GEP, CD8A and CXCL9 expression showed significant predictive power across all cancer types." (PMID 37277866, 2023). "To detect the logarithm fold change (logFC) in the expression of the four genes TCF7, LEF1, CD8A, and CD8B in different cancers, we investigated the transcriptomic profiles retrieved from the TCGA database." (PMID 35588138, 2022). "The pie chart showed that the heterozygous CNVs of all 6 genes (CD68, MRC1, CD8A, CD8B, CD163, and CLEC5A) was more frequent in various cancers." (PMID 35979347, 2022). "In order to precisely describe what chemokine is involved in T-cell homing, a transcriptomic approach, conducted in seven types of human cancers, proposed that CCL5 and CXCL9 expression is correlated with CD8A expression in the tumors." (PMID 36429101, 2022).
cancer (continued). "We recently found that the PI3K/PTEN signaling pathway is driving CD8α+DCs expressing PD-L1 and PD-L2 and impairing efficient CD8 T-cell responses in two different cancer models in a myeloid-PTEN (PTENΔmye) specific mouse model." (PMID 35514976, 2022). "Next, we evaluated the correlation between the DNA methylation and mRNA expression of CLEC5A and immune-related gene (MRC1, CD163, CD8A, CD8B, CD68) in pan-cancer." (PMID 35979347, 2022). "This study aimed to establish a novel four‐gene signature (CD8A, CD8B, TCF7, and LEF1) to provide a prognostic immunotherapy biomarker for different cancers." (PMID 35588138, 2022). "GSCALite was utilized to identify the SNV frequency of all 6 genes (CD68, MRC1, CD8A, CD8B, CD163, and CLEC5A) in various cancers." (PMID 35979347, 2022). "They found that CD8α+ DCs, a population of lymph node‐resident cDC1, acquired both CFSE and PKH26 from irradiated cancer cells but only PKH26 from live cancer cells." (PMID 35959554, 2022). "CD8A, a crucial protein on T cells surface, is highly correlated with LPAR6 expression in LUAD which are types of cancers with better prognosis." (PMID 34769557, 2021). "Flow cytometry was performed to identify and collect the cancer cells marked by EPCAM, T cells marked by CD3D, CD8+ T cells marked by CD8A, and CD4+ T cells marked by CD4 in the GGN-ADC and SADC samples." (PMID 33083004, 2020). "In stark contrast, pS14-WWOX7-21 peptide induces the expansion of spleen CD8α+ T and CD19+ B cells and dramatically enhances cancer growth in vivo." (PMID 31752354, 2019). "DCs, especially the Batf3-dependent sub-family characterized by CD8α and/or CD103 expression, are essential for anti-cancer immune responses." (PMID 26343581, 2015). "In the gene co‐expression network, we observed that YRDC was associated with the expression of multiple immune cell signature genes at the pan‐cancer level, including T‐cell signature genes (CD3D, CD4, CD8A, CD8B), B‐cell signature genes (CD19, MS4A1), and multiple immunoglobulin genes." (PMID 40898423, 2025). "Functionally, the CD8 SP (particularly CD8α/α) and DN Allo15CAR33-NKT cells displayed similar characteristics, suggesting a pro-inflammatory and highly cytotoxic profile, which is advantageous for cancer immunotherapy." (PMID 39893165, 2025). "Additionally, we manually delineated the carcinoma region and quantified the number of CD8+ T-cell spots as spots with CD8A and CD3D or CD3E expression levels above their respective 75th percentiles." (PMID 41382107, 2025). "CD8A expression in the TME is a positive indicator for cancer immunosurveillance, signifying the presence of cytotoxic T lymphocytes or CD8 + T cells, which are central to anti-cancer immunity." (PMID 38777826, 2024). "Consistently, analysis of the LUSC cohort profiled by the TCGA also revealed that OTUB2 was more highly expressed in cancer tissues than in normal tissues, while the CTL signature genes CD8A and GZMB were expressed at significantly lower levels in cancer tissues than in normal tissues." (PMID 38167274, 2024). "CD8A, an important glycoprotein on the surface of T cells involved in intercellular interactions in the immune response, is highly correlated with SIRT2 expression in LUAD which are types of cancers with better prognosis." (PMID 36844923, 2022). "Nonetheless, the lack of investigation into the role of CD8A in TME predisposed to limitations in its clinical use, necessitating further research into its underlying mechanisms in the pan-cancer cohort." (PMID 36035168, 2022). "Moreover, in CRC, the number of mutations or neoantigens was significantly higher in TIMT type I (high PD-L1 and CD8A/CYT) than in TIMT type II (low PD-L1 and CD8A/CYT) cancers." (PMID 35842707, 2022).